PDPN (podoplanin)
Diseases named in the same sentence as PDPN in open-access papers (continued):
Sharing a sentence is not in itself a finding about the gene and the disease.
melanoma (48 papers, 2007 to 2025). A malignant, usually aggressive tumor composed of atypical, neoplastic melanocytes. "Integrated multi-database analysis revealed a significant positive association between PDPN and the immunosuppressive checkpoint receptor PD-L1 in melanoma transcriptomes." (PMID 41573582, 2025). "In melanoma, expression of PDPN by intratumoral cancer-associated fibroblasts (CAFs) is correlated with increased sentinel lymph node metastases, with PDPN-expressing CAFs enhancing local immunosuppression through cytokine secretion and immune modulation." (PMID 41573582, 2025). "We used a podoplanin-expressing murine melanoma cell line and CLEC-2-deficient mice to establish a mouse model of experimental pulmonary metastatic melanoma." (PMID 38561690, 2024). "Firstly, we have demonstrated that PDPN expression was closely associated with melanoma development." (PMID 38167452, 2024). "Various studies have shown that PDPN expression is significantly elevated in melanoma clinical tissue and cells, and is frequently associated with poor prognosis." (PMID 38167452, 2024). "We have demonstrated that PDPN was strongly associated with the proliferation, migration, and invasive properties of melanoma cells." (PMID 38167452, 2024). "PDPN expression promotes the dedifferentiation of melanoma cells, and the loss of PDPN restores pigmentation and melanocyte differentiation." (PMID 35159384, 2022). "Podoplanin is also expressed in normal peritumoral cells, such as cancer-associated fibroblasts in melanoma and keratinocytes in extramammary Paget’s disease, which promote tumor progression and predict aggressive behavior and poor prognosis." (PMID 35163233, 2022). "In preclinical melanoma models, enlargement of tumor-draining LNs preceding metastasis is associated with an increased number and gradual reprogramming of key signaling pathways of PDPN+ FRCs." (PMID 38038708, 2024). "Collectively, these results revealed that PDPN may be strongly associated with the formation and development of melanoma." (PMID 38167452, 2024). "Previous studies have shown that MASL associates with PDPN on the membrane of melanoma cells." (PMID 25826087, 2015). "Similarly, we observed loss of LYVE-1 expression on PDPN+ vessels proximal to melanoma tumor nests." (PMID 38361951, 2024). "Through analysis of the TCGA database, we found that PDPN was significantly associated with the development of several common types of tumors, including adenomas and adenocarcinomas, cystic, mucinous, and serous neoplasm, ductal and lobular neoplasia, and melanoma." (PMID 38167452, 2024). "Although the protumoral roles of PDPN are well documented, its precise mechanistic contributions to immune evasion in melanoma remain only partly defined and require further elucidation." (PMID 41573582, 2025). "Our tissue microarray analyses revealed a correlation between PDPN and PD-L1 expression in both primary (46.5% co-expression) and metastatic (43.8% co-expression) melanoma specimens." (PMID 41573582, 2025). "Triple immunofluorescence staining showed limited co-expression of PDPN and PD-L1 in benign nevi, whereas marked upregulation and co-expression were observed in primary (e.g., #3, #22) and metastatic (e.g., #110) melanoma lesions." (PMID 41573582, 2025). "In conclusion, our findings define podoplanin (PDPN) as a central mediator of tumor immune escape in melanoma, promoting PD-L1 upregulation in tumor cells via activation of the Wnt/β-catenin signaling axis." (PMID 41573582, 2025). "Western blot analysis demonstrated a marked reduction in total PD-L1 protein levels in A375 and B16-F10 melanoma cells upon PDPN depletion." (PMID 41573582, 2025). "In the present study, we establish that inhibition of PDPN using the CY12-RP2 inhibitory peptide attenuates melanoma progression in multiple murine models, concomitant with reduced functional exhaustion of tumor-infiltrating CD8+ T cells." (PMID 41573582, 2025).
melanoma (continued). "Mechanistically, CY12-RP2 acts by suppressing PDPN-mediated activation of the Wnt/β-catenin signaling cascade, resulting in diminished PD-L1 expression in melanoma cells and subsequent activation of CD8+ T cell-mediated antitumor responses." (PMID 41573582, 2025). "Our previous study has shown that PDPN hyperactivates the Wnt/β-catenin pathway in melanoma by stabilizing β-catenin, promoting its nuclear translocation and complex formation with LEF/TCF, and driving oncogenic transcriptional programs." (PMID 41573582, 2025). "Our study confirms and expands upon these findings by establishing PDPN as an upstream regulator of β-catenin-dependent PD-L1 transcription in melanoma." (PMID 41573582, 2025). "This investigation is necessary to realize PDPN’s potential as a therapeutic target for improving antitumor immunity, especially in melanoma." (PMID 41573582, 2025). "Taken together, these findings establish that PDPN controls the expression of cell surface PD-L1 in melanoma cells." (PMID 41573582, 2025). "While PDPN has attracted attention as a potential immunotherapeutic target, its specific mechanistic functions in melanoma, particularly regarding crosstalk with immune cells in the tumor microenvironment, remain inadequately clarified." (PMID 41573582, 2025). "This study has demonstrated the important role of PDPN in the progression of melanoma and formation of immunosuppressive environment, and provided a potential approach of treating melanoma using the novel CY12-RP2 peptide." (PMID 38167452, 2024). "This study aimed to investigate the role of the PDPN-platelet CLEC-2 interaction in melanoma pulmonary metastasis." (PMID 38561690, 2024). "In melanoma, PDPN is overexpressed in the cancer cells, and promotes melanoma cells growth and metastasis through activating the Wnt/β-catenin pathway." (PMID 38167452, 2024). "We used the murine melanoma cell line B16-F0, which has two populations with differential podoplanin expression, to perform the experiments." (PMID 38561690, 2024). "PDPN was overexpressed in melanoma tissue and cells, and inhibited melanoma cells proliferation, migration, and metastasis by blocking the EMT and Wnt/β-catenin pathway." (PMID 38167452, 2024). "The immunofluorescence, SPR assay, and flow cytometry were used to identify the binding specificity of CY12-RP2 with PDPN in melanoma cells." (PMID 38167452, 2024). "We then performed immunofluorescence, SPR assay, and flow cytometry to identify the binding specificity of CY12-RP1 and CY12-RP2 with PDPN in melanoma cells." (PMID 38167452, 2024). "Then, we investigated the viability of PDPN expression in melanoma as a prognostic marker through the OncoLnc database, and found that high PDPN expression in clinical patients predicted a poor survival rate." (PMID 38167452, 2024). "Our study indicates that the PDPN-CLEC-2 interaction promotes experimental pulmonary metastasis in a mouse melanoma model." (PMID 38561690, 2024). "PDPN expression was first analyzed in 112 human melanoma tissue microarrays and melanoma cell lines." (PMID 38167452, 2024). "In conclusion, our present study shows that the podoplanin-CLEC-2 interaction promotes experimental pulmonary metastasis in a mouse melanoma model." (PMID 38561690, 2024). "Our results shed light on the importance of PDPN in melanoma progression, and also provided a novel PDPN-targeting peptide for melanoma treatment." (PMID 38167452, 2024). "At present, research that focuses on the effects of PDPN on the melanoma tumor microenvironment is limited, and therapeutic peptides targeting PDPN for the prevention and/or treatment of melanoma have also not been reported." (PMID 38167452, 2024). "We discovered that the podoplanin-CLEC-2 interaction promoted experimental melanoma pulmonary metastasis through platelet and tumour cell aggregation." (PMID 38561690, 2024).
melanoma (continued). "In our current study, we investigated the role of the PDPN-CLEC-2 interaction in melanoma pulmonary metastasis and its relationship with platelets." (PMID 38561690, 2024). "In our experiment, platelets and melanoma cells aggregated in vitro only when podoplanin and CLEC-2 were present at the same time." (PMID 38561690, 2024). "We herein sought to gain a better insight into the function of PDPN and the potential of an antagonist in melanoma treatment." (PMID 38167452, 2024). "According to the statistics, we found that 73.9% of 111 melanoma cases expressed PDPN (76.6% in 94 primary samples and 58.8% in 17 metastasis samples)." (PMID 38167452, 2024). "A recent study in melanoma revealed that PDPN functions as an immunosuppressive molecule in T cells." (PMID 38470096, 2024). "To further investigate the potential anti-tumor effect of PDPN antagonist on melanoma, we used a Ph.D.TM-12 Phage Display Peptide Library to screen for a PDPN antagonist peptide." (PMID 38167452, 2024). "Above all, the role of the podoplanin-CLEC-2 interaction in experimental melanoma pulmonary metastasis partially depends on the Syk signalling pathway." (PMID 38561690, 2024). "A retrospective study demonstrated that 69.1% of 55 melanoma cases expressed PDPN, and over-expression of PDPN promoted cancer migration and EMT, thereby accelerating invasion and metastasis." (PMID 38167452, 2024). "The results showed that PDPN protein levels were dramatically upregulated in primary melanoma specimens and metastasis samples." (PMID 38167452, 2024). "In our experiments, we used the B16 melanoma cell line to demonstrate the role of podoplanin in melanoma pulmonary metastasis because B16 cells express podoplanin, which is involved in platelet aggregation." (PMID 38561690, 2024). "To investigate the effects of PDPN on melanoma cells, we used RNA interference to knockdown the PDPN in A375, and used overexpression lentiviral vectors to upregulate the PDPN in A875." (PMID 38167452, 2024). "GPVI and CLEC-2 have been shown to interact with e.g., galectin-3 and podoplanin, respectively, both of which are upregulated in melanoma." (PMID 39695652, 2024). "Taken together, these data demonstrated that PDPN is overexpressed in melanoma, closely correlated with poor prognosis, and play facilitating roles in melanoma cell proliferation, metastasis, and invasion." (PMID 38167452, 2024). "As observed in the melanoma, PDPN+PDGFRα+ CAFs were reorganized but still present in similar numbers in tumors lacking ADAM12+ MSCs, and the vasculature displayed increased pericyte coverage and ICAM1 expression." (PMID 37798557, 2023). "Melanoma patients with CAFs expressing podoplanin, a mucin-type transmembrane protein, have tumors with greater tumor thickness, more lymph node metastases and poorer survival than patients with podoplanin-negative CAFs." (PMID 37046676, 2023). "In vivo, the inhibition of CLEC-2 expression was effective at suppressing the microvessel density of melanoma and reducing the interaction with PDPN to block malignant melanoma growth and lung metastasis." (PMID 37762054, 2023). "The role of podoplanin has also been elucidated in various skin cancers and the targeted therapy of melanomas using anti-podoplanin antibodies has already been evaluated in preclinical trials." (PMID 35163233, 2022). "We generated a lymphatic score for melanoma samples based on the relative expression levels of PDPN, LYVE1, and VEGFC28, and found that GPR182 expression significantly correlated with lymphatic score in melanoma." (PMID 35013216, 2022). "In vivo, mice injected with podoplanin (+) and podoplanin (−) melanoma cells (1:1 mix) produced tumors containing a higher proportion of podoplanin (+) cells, which were observed beyond the tumor boundary as single rounded cells." (PMID 35163233, 2022).
melanoma (continued). "Since melanoma growth is partially regulated via podoplanin-CLEC-2 mediated platelet aggregation, SZ168 is thought to suppress tumor growth by inhibiting the interaction between tumor podoplanin and platelet CLEC-2." (PMID 35163233, 2022). "In this study, we manually searched the literature available in Pubmed using the following keywords: podoplanin, skin, cutaneous, melanoma, squamous cell carcinoma, skin cancer, wound healing, psoriasis, and dermatitis." (PMID 35163233, 2022). "A cancer-specific mouse–dog chimeric anti-podoplanin antibody, P38B, has also proceeded to phase I/II clinical trial in dogs with melanomas to investigate its safety and anti-tumor effects." (PMID 35163233, 2022). "We demonstrated that KCNE4 expression is also present in podoplanin-positive cells in human melanoma metastatic LNs." (PMID 35915077, 2022). "PDPN expression in murine melanoma cells drives the rounded cell morphology, increasing motility and invasion." (PMID 35159384, 2022). "A retrospective analysis of 55 cases of melanoma revealed that podoplanin was expressed in 69.1% of the tumor cells; however, its expression did not correlate with tumor progression." (PMID 35163233, 2022). "Recently, podoplanin has attracted considerable attention as a new therapeutic target for melanoma because both melanoma cells and CAFs express podoplanin." (PMID 35163233, 2022). "Other functional blocking monoclonal antibody (mAb, SZ168) against the extracellular domain of human PDPN also significantly inhibited the growth and pulmonary metastasis of human malignant melanoma." (PMID 34322381, 2021). "In mice inoculated with PDPN-expressing B16F10 melanoma cells, CLEC2 depletion by anti-CLEC2 mAb 2A2B10 injection reduced plasma levels of inflammatory cytokines and lung metastasis, resulting in prolonged survival compared to control mice." (PMID 34987523, 2021). "Confocal microscopy analysis confirmed the presence of LCMV-NP in melanoma cells (arrows) and in PDPN+ FSCs located mainly at the tumor margin (arrowheads)." (PMID 34354077, 2021). "It is not yet clear how PDPN contributes to an aggressive tumour phenotype, but knockdown of PDPN in oral melanoma cell lines inhibits cell migration and proliferation, while promoting tumour cell apoptosis." (PMID 34822659, 2021). "Following the data of the preclinical study using the experimental healthy dog, we conducted a phase I/II clinical trial for the evaluation of clinical safety and potential efficacy of anti-PDPN antibody therapy in dogs with dPDPN-positive malignant melanoma." (PMID 33238582, 2020). "Increased podoplanin expression in CAFs and a positive correlation between CAF podoplanin expression and poor prognosis were demonstrated in lung adenocarcinoma, the invasive ductal carcinoma of breast and pancreas, and melanoma." (PMID 32532126, 2020). "The reactivity of P38Bf against canine podoplanin (dPDPN) expression on the cell surface of canine melanoma cell lines was evaluated using flow cytometric analysis." (PMID 33238582, 2020). "We first demonstrated that a cancer-specific mouse–dog chimeric anti-PDPN antibody (P38Bf) induces antibody-dependent cellular cytotoxicity (ADCC) by recognizing endogenously expressed canine podoplanin (dPDPN) on canine malignant melanoma cells." (PMID 33238582, 2020). "Intravenously administered αMSH-PEG-Cy5-C′ dots in mice with B16-F10 melanoma showed accumulation of the silica nanoparticles in both PDPN+ melanoma cells (4.07%) and F4/80+ macrophages (1.48%)." (PMID 32013538, 2020). "Our results indicate that SZ168 antibody has high potential for the development of novel antibody-based immunotherapy against PDPN-expressing tumors such as human malignant melanoma." (PMID 31208371, 2019). "Our data show that the growth of C8161 malignant melanoma is regulated via PDPN-CLEC-2-mediated platelet aggregation." (PMID 31208371, 2019).
melanoma (continued). "It was also shown that PDPN present on the surface of fibroblasts increases the motility and viability of melanoma cells." (PMID 28938000, 2017). "As with mouse melanoma cells, PDPN expression was also much higher in human melanoma cell lines than normal skin." (PMID 22844530, 2012). "Consistent with its role in tumor cell invasion and metastasis, malignant B16 melanoma cells expressed higher levels of PDPN and migrated significantly better than syngeneic nontransformed Melan-a melanocytes." (PMID 22844530, 2012). "Robust PDPN expression was found 100% of the 8 melanoma samples examined from cancer patients in this study." (PMID 22844530, 2012). "In any case, robust PDPN expression was seen in all of the melanoma cell lines that we examined, indicating that melanoma cells themselves express PDPN." (PMID 22844530, 2012). "Therefore, defining the molecular basis of PD-L1 regulation is critically important, and PDPN’s involvement in this regulatory axis stands as a key unresolved issue in melanoma immunobiology." (PMID 41573582, 2025). "Immunofluorescence analysis further revealed that β-catenin expression is significantly reduced in A375 and B16-F10 melanoma cells following PDPN knockdown, and that both total and S552-phosphorylated β-catenin levels are significantly decreased upon PDPN depletion or CY12-RP2 treatment." (PMID 41573582, 2025). "Collectively, these results suggest that PDPN may function as a potential therapeutic hub, coordinating the activation of immunosuppressive checkpoints and the exclusion of T cells in melanoma." (PMID 41573582, 2025). "Evaluation of melanoma data from The Cancer Genome Atlas (TCGA) revealed strong positive correlations between PDPN expression and several immune checkpoint receptors, including PD-L1, CTLA4, LAG3, TIGIT, and BTLA, with the association with PD-L1 (CD274) being the most prominent (r=0.504, p<0.001)." (PMID 41573582, 2025). "Taken together, these results indicated that CY12-RP2 could specifically bind with PDPN, inhibit the cell proliferation, and promote apoptosis in melanoma cells both in 2D cells cultures and 3D cellular spheres." (PMID 38167452, 2024). "Furthermore, immunofluorescence also verified the differential expression of PDPN in melanoma cell lines." (PMID 38167452, 2024). "Taken altogether, our study investigated the role of PDPN in melanoma, and confirmed that PDPN could promote melanoma growth and metastasis through activating the Wnt/β-catenin pathway." (PMID 38167452, 2024). "In the current study, we firstly demonstrated that the overexpression of PDPN could promote the proliferation, morphology, migration, and invasion of melanoma through activating Wnt/β-catenin pathway." (PMID 38167452, 2024). "We thus established PDPN + and PDPN- B16-F0 murine melanoma cells." (PMID 38561690, 2024). "In our study, we found that PDPN was overexpressed in melanoma clinical tissue and cells, and PDPN could promote melanoma cell migration and invasion through activating the Wnt/β-catenin pathway." (PMID 38167452, 2024). "Overall, these results indicated that PDPN could induce the EMT process in melanoma cells via activating the Wnt/β-catenin signaling pathway." (PMID 38167452, 2024). "PDPN antagonistic peptide, CY12-RP2, could specifically bind with PDPN, suppressing melanoma various functions inducing apoptosis in both melanoma cells and 3D spheroids." (PMID 38167452, 2024). "Development of PDPN targeted therapeutics may be a useful method to enhance the effects of immunotherapy in melanoma." (PMID 38167452, 2024). "Several preclinical studies have demonstrated that podoplanin could be a therapeutic target in several malignancies, including melanomas." (PMID 35163233, 2022).